FGFR1 (fibroblast growth factor receptor 1)
Diseases named in the same sentence as FGFR1 in open-access papers (continued):
Sharing a sentence is not in itself a finding about the gene and the disease.
osteosarcoma (continued). "RSK2 was shown to bind directly to the C-terminal tail of FGFR1 and direct receptor endocytosis in human osteosarcoma cells." (PMID 27476168, 2016). "On the other hand, RSK2 appears to directly phosphorylate and regulate endocytosis of FGFR1 in osteosarcoma cells." (PMID 27476168, 2016). "Recent studies have shown that also FGF12 has anti-apoptotic properties in the osteosarcoma U2OS cell line overexpressing FGFR1 (U2OS-R1), but this has not yet been linked to drug resistance." (PMID 34830951, 2021). "To test whether the MRTF/SRF pathway is also responsible for FGFR1 regulation in cancer cells, we treated the osteosarcoma cell line MG63 with the MRTF/SRF inhibitor." (PMID 33067523, 2020). "However, little is known on the biological and functional significance of miR-133b/FGFR1 regulation in osteosarcoma." (PMID 30574019, 2018). "Furthermore, pharmacological blockade of FGFR1 has also been shown to decrease lung metastases in an osteosarcoma animal model." (PMID 27685995, 2016). "Taken together, these results suggested that FGFR inhibitors might show some utility in osteosarcoma, but that factors in addition to FGFR1 and FGFR2 amplification might explain drug sensitivity in this setting." (PMID 26947069, 2016). "FGFR1 is amplified in the osteosarcoma T30 but deleted in the tubulopapillary carcinoma T52." (PMID 24098698, 2013). "Here, we investigated the effect of sulfatinib, a multi-targeted tyrosine kinase inhibitor (TKI) of FGFR1, CSF1R, and VEGFR1–3, on the treatment of osteosarcoma (OS)." (PMID 37361567, 2023). "We used several FGFR1-positive cell lines: lungsquamous cell carcinoma NCI-H520, lung large cell carcinoma NCI-H1581,and the osteosarcoma cell line G-292." (PMID 34855396, 2021). "FGFR1 protein expression was also detected in MC3T3-E1 Subclone 4 osteoblastic cells and MG-63 human osteosarcoma cells." (PMID 31217507, 2019). "The first set comprised of osteosarcoma cells (U2OS), characterized by a very low FGFR1 levels, together with U2OS cells stably transfected with FGFR1 (U2OS-FGFR1)." (PMID 30029518, 2018). "FGFR1 and CDH11 are markers of osteoclasts or osteosarcoma cells." (PMID 38218960, 2024). "FGFR1 and CDH11 were mainly expressed on 8 clusters of cells, thus it could be determined that the 8 clusters were osteoblasts or osteosarcoma cells." (PMID 38218960, 2024). "Other examples include miR-133b direct downregulation of FGFR1 expression and RAS-MAPK/PI3K-AKT signaling in osteosarcoma cells, miR-889-3p decreasing FGFR2 expression in cervical cancer and miR-24-3p downregulation of FGFR3 expression in multiple myeloma (MM) and lung adenocarcinoma." (PMID 34068954, 2021). "In osteosarcoma MG63 cells, MRTF/SRF inhibition also led to decreased FGFR1 expression." (PMID 33067523, 2020). "Although only one experiment with an osteosarcoma cell line (MG63) is presented here, our study may open up new potential targets for FGFR1 regulation in cancer cells." (PMID 33067523, 2020). "The FGFR1 and FGFR2 KGDs suggested that osteosarcoma models might be especially sensitive to small molecule FGFR inhibitors." (PMID 26947069, 2016). "However, apatinib and cabozantinib, which do not target FGFR1, can effectively treat osteosarcoma." (PMID 32984034, 2020). "This osteosarcoma selective effect was independent of FGFR1 or FGFR2 amplification status and was also apparent when FGFR1 or FGFR2 amplified tumor cell lines were excluded from the analysis (AZD4572, p = 7.2 × 10−3 and PD173074, p = 4.3 × 10−2)." (PMID 26947069, 2016). "Cediranib, a multi-target FGFR1 TKI, is not effective in the osteosarcoma treatment." (PMID 32984034, 2020).
hypogonadotropic hypogonadism (36 papers, 2012 to 2025). Abnormal ovarian or testicular function due to insufficient hormonal stimulation from the hypothalamic-pituitary axis. "A case of a patient with hypogonadotropic hypogonadism and persistent growth hormone (GH) deficiency whose genetic analysis uncovered a pathogenic missense heterozygous variant in exon 15 of the FGFR1 gene is presented." (PMID 40434549, 2025). "Since hypogonadotropic hypogonadism and GH deficiency are comorbid in pathogenic FGFR1 variants, it is necessary to carefully monitor the possibility of KS and GHD comorbidity." (PMID 40141355, 2025). "FGFR1-associated congenital hypogonadotropic hypogonadism with SHFM (MIM #147950) is another presentation of this malformation, which can be explained by FGFR1 expression in early limb bud expression and it being crucial for bone formation." (PMID 38275609, 2024). "FGFR1 mutation has also been described in normosomic hypogonadotropic hypogonadism; 20% of patients with this mutation have demonstrated reversal of their hypogonadism." (PMID 37294556, 2023). "For example, variants in FGFR1 are known to be associated with encephalocra-niocutaneous lipomatosis, Hartsfield syndrome, hypogonadotropic hypogonadism, osteoglophonic dysplasia, and Pfeiffer syndrome." (PMID 37285546, 2023). "The findings from the present study expand the mutational spectrum of ANOS1 and FGFR1 in hypogonadotropic hypogonadism." (PMID 31996231, 2020). "Following the discovery of this FGFR1-likely pathogenic variant, a clinical evaluation focusing on potential hypogonadotrophic hypogonadism and hypo/anosmia has been proposed." (PMID 31652620, 2019). "According to the OMIM database, FGFR1 is associated with the autosomal dominant disorders Hartsfield syndrome (#615465), hypogonadotropic hypogonadism (#147950), Jackson–Weiss syndrome (MIM #123150), and Pfeiffer syndrome (MIM #101600), exhibiting an incomplete penetrance." (PMID 40650163, 2025). "For example, gain-of-function mutations in the region of the immunoglobulin domain of fibroblast growth factor receptor 1 (FGFR1) result in Pfeiffer syndrome and osteoglophonic dysplasia, whereas loss-of-function mutations throughout the protein cause hypogonadotrophic hypogonadism." (PMID 29056714, 2016). "The results may provide new insights into the molecular mechanism by which the variant of FGFR1 impairs gonadal steroidogenesis, in addition to authentic hypogonadotropic hypogonadism, due to the impairment of GnRH neurons, leading to primary, as well as secondary, hypogonadism." (PMID 40141355, 2025). "Congenital central hypogonadism is believed to be caused by genetic pathogenic variants, with genes such as ANOS1, FGFR1, FGF8, PROKR2, and PROK2 being implicated." (PMID 39817151, 2025). "We also found novel FGFR1 and SEMA3A variants that suggest an oligogenic mechanism in PSIS and EPP, as seen in patients with hypogonadotropic hypogonadism." (PMID 39156017, 2024). "Other rare and novel pathogenic variants in ANOS1, WDR11, FGFR1, RNF216, and CHD7 genes were also found in patients with Congenital Hypogonadotropic Hypogonadism." (PMID 38637882, 2024). "Additional association of FGFR1 and CPHD was reported in a case report describing a 16-year-old male with micropenis, undescended testes, flat nasal root in conjunction with GHD and hypogonadotropic hypogonadism but normal MRI and normal smell test." (PMID 40434549, 2025). "Here, we show that a majority of patients with KLB mutations (9/13) exhibit hypogonadotropic hypogonadism with some degree of metabolic defect (i.e. overweight, insulin resistance, and/or dyslipidemia), consistent with the metabolic role of FGF21/KLB/FGFR1 pathway." (PMID 28754744, 2017). "Additionally, genetic causes of isolated hypogonadotropic hypogonadism such as KAL1, FGFR1/FGF8, PROKR2/PROK2, CHD7, or GNRH1 gene mutations have not been studied because the patient had a normal puberty and regular menstruation before the amenorrhea." (PMID 26266058, 2015).
hypogonadotropic hypogonadism (continued). "Interestingly, a separate study has identified a different balanced translocation involving the TNS3 gene, in this case also affecting the FGFR1 gene, with the patient displaying hypogonadotropic hypogonadism and cleft lip and palate." (PMID 23809228, 2013). "To date, mutations in FGFR1 account for less than 10% of patients with congenital hypogonadotropic hypogonadism (CHH) involving KS and nIHH, and among them, even fewer have undergone functional analysis, and thus, the correlation between phenotype and genotype cannot be clearly verified." (PMID 33299522, 2020).
colorectal cancer (35 papers, 2010 to 2026). A primary or metastatic malignant neoplasm that affects the colon or rectum. "Functionally, high expression of FGFR1 has been shown to be associated with increased proliferation and invasion of colorectal cancer cells; MYO6 is known to be an oncogene in CRC, while CDK9 has been used as a potential target for the treatment of CRC." (PMID 38877540, 2024). "FGFR1 amplification and overexpression has been reported in colorectal cancer and associated with the presence of liver metastasis." (PMID 25193853, 2014). "Meanwhile, a Phase I study for FGFR1–3 inhibitor rogaratinib investigated 866 solid cancer patients, including 46 colorectal cancer patients, and showed that the tumor of only one patient had FGFR mRNA overexpression." (PMID 32708005, 2020). "Recent studies indicated that miR-214-3p inhibited proliferation or tumor progression by targeting FGFR1 in the differentiation process of osteogenic mesenchymal stem cells and colorectal cancer, which was consistent with our research." (PMID 31492847, 2019). "In a study of colorectal cancer, the copy number gain of FGFR1 significantly correlated with worse outcomes." (PMID 28056982, 2017). "To assess the clinical relevance of these in vitro observations, we performed preliminary immunohistochemical stainings for FGF-2 and FGFR1 on human colorectal cancer samples." (PMID 25973543, 2015). "Further, a reciprocal relationship between Fgfr1 and Fgfr3 was observed in colorectal carcinoma cells." (PMID 20405041, 2010). "FGFRL1 thus acts as a negative regulator of FGFR1 signaling and loss of function mutations described here may represent a novel mechanism of FGF signaling activation in colorectal cancer." (PMID 25193853, 2014). "Several genes with high-frequency and important CNVs, namely, MYC, FGFR1, CCNE1, and CCND3 have been observed in lung and colorectal cancer samples." (PMID 35402275, 2022). "In colorectal cancer, genomic alterations in FGFR such as gene amplifications are not as common as fusion in FGFR3 or gene copy number gain in FGFR1." (PMID 32580713, 2020). "Only few publications have described alterations of FGFR1 or other FGFR genes up to now which are basically in line with our findings in primary colorectal cancers." (PMID 30181810, 2018). "It was reported recently that amplification of MET, FGFR1 and ERBB2 was involved in EGFR therapeutic resistance in colorectal cancer." (PMID 27738318, 2016). "FGFR1 has been reported to have both oncogenic and tumor suppressive potential and the tyrosine kinase RET has long been established as a classic proto-oncogene but was found to act as a TSG in colorectal carcinomas." (PMID 36726722, 2022). "For example, a Phase I clinical trial for FGFR1–3 inhibitor AZD4547 for 30 solid cancer patients with FGFR mutations, amplifications, or fusions included three colorectal cancer patients, but no data on their sensitivity to AZD4547 were available." (PMID 32708005, 2020). "In addition, among the four FGFRs (FGFR1-4), the significance of FGFR2 in colorectal cancer has been clearly demonstrated." (PMID 24758762, 2014). "Moreover, Regorafenib, a multi-kinase inhibitor that targets FGFR1 among other RTKs, was recently approved by the FDA for the treatment of advanced colorectal cancer, but predictive biomarkers for this indication are not yet currently available." (PMID 25193853, 2014).
hepatocellular carcinoma (35 papers, 2012 to 2025). A malignant tumor that arises from hepatocytes. "The upregulation of PLAUR, S100A4, S100A6, and FGFR1 in mature B cells was involved in disease‐associated cellular migration and tissue invasion, which may influence hepatocellular carcinoma with persistent liver injury." (PMID 41190282, 2025). "In hepatocellular carcinoma, FGFR1 activation promotes tumor-initiating cell enrichment and angiogenesis, contributing to acquired sorafenib resistance." (PMID 41226200, 2025). "The FGFR1 gene has recently been found to be expressed in hepatocellular carcinoma, and the aberrant FGF/FGFR signalling in HCC initiation, progression, and therapy status offers fresh information on how to treat HCC." (PMID 40225267, 2025). "Upregulation of FGFR1 and VEGFR3 expression in the MCB1‐deficient hepatoma cells was further confirmed by immunofluorescence staining." (PMID 39402741, 2024). "A couple of non-FGFR1-derived circRNAs have been reported to promote FGFR1 expression, such as circ_SNX27 and circRAPGEF5, which functioned as miRNA sponges for miR-637 (in hepatocellular carcinoma) and miR-198 (in papillary thyroid carcinoma) respectively." (PMID 37993879, 2023). "FGFR1 expression was promoted by circ_SNX27 (in hepatocellular carcinoma) and circRAPGEF5 (in papillary thyroid carcinoma), which suppressed miR-637 and miR-198 respectively." (PMID 37993879, 2023). "Though FGFR4 is the major FGFR present in mature hepatocytes, elevated expression of FGFR1 has been observed in hepatocellular carcinoma (HCC) and contributed to tumor development." (PMID 36263162, 2022). "In a study carried out on hepatocellular carcinoma tissues, a significant positive correlation was found between the expression levels of FGFR1 protein and those of UCA1." (PMID 31319040, 2020). "Evaluated UCA1 contributes to progression of hepatocellular carcinoma through decreasing miR-216b and activation the FGFR1/ERK signaling pathway." (PMID 27893417, 2017). "LncRNA urothelial carcinoma-associated 1(lncRNA-UCA1) through inhibition of miR-216b and activation of FGFR1/ERK signaling pathway in hepatocellular carcinoma." (PMID 28404901, 2017). "For example, excessive CUDR contributes to progression of hepatocellular carcinoma through inhibition of miR-216b and activation of FGFR1/ERK signaling pathway." (PMID 27833137, 2016). "In the context of tumor angiogenesis, DJ-1 has been identified as a key secreted factor that promotes FGFR1 activation in endothelial cells by enhancing phosphorylation at these residues, thereby contributing to sorafenib resistance in hepatocellular carcinoma (HCC)." (PMID 41226200, 2025). "Expression of FGFR1 and FGFR4 was generally very low in keratinocytes in comparison to human primary fibroblasts (HPF) or HepG2 hepatoma cells, respectively." (PMID 39340759, 2024). "Accordingly, depletion of MCB1 in hepatoma cells resulted in the accumulation of FGFR1 and VEGFR3, as well as ubiquitinated FGFR1 and ubiquitinated VEGFR3." (PMID 39402741, 2024). "Conversely, concurrent knockdown of FGFR1 and VEGFR3 recapitulated the targeted drug‐resistant phenotype and abolished downstream signaling in MCB1 knockdown hepatoma cells, while knockdown of either of them showed a limited effect." (PMID 39402741, 2024). "In hepatocellular carcinoma, MIR296 inhibits the proliferative capacity and progression of the cell cycle and induces apoptosis blocking the transcription of the FGFR1 proto-oncogene." (PMID 32582296, 2020). "In hepatocellular carcinoma, upregulated UCA1 contributes to the progression of cancer by counteracting the inhibitory effect of miR-216b and activating the FGFR1/ERK signaling pathway." (PMID 28074092, 2016). "Radio-iodinated FGF19 exhibited an affinity with a Kd value of 303 pM to the FGFR1-KLB complex expressed on the T-Rex 293 cells, and 778 pM to a hepatocellular carcinoma cells expressing FGFR4 and KLB." (PMID 22442730, 2012).
hepatocellular carcinoma (continued). "More importantly, our data showed that the interference of MCB1 increased FGFR1 and VEGFR3 activation and sensitized hepatoma cells to targeted drugs, suggesting that the interaction between MCB1 and FGFR1 or VEGFR3 determines the HCC cell response to sorafenib and lenvatinib." (PMID 39402741, 2024). "gluclncRNA (HULC) is up-regulated in hepatocellular carcinoma (HCC), directly binds LDHA, enhances the binding of LDHA to fibroblast growth factor receptor type 1 (FGFR1), thus promoting the glycolysis, proliferation, and progression of HCC cells." (PMID 34404767, 2021).